LEP (leptin)
Diseases named in the same sentence as LEP in open-access papers (continued):
Sharing a sentence is not in itself a finding about the gene and the disease.
Obesity (continued). "Consistent with the reduction of obesity, treatment of KY19334, but not orlistat, specifically improved their metabolic parameters including total cholesterol, HDL-cholesterol, leptin, and resistin as well as the blood glucose level and insulin sensitivity." (PMID 36450849, 2022). "Both groups including obese children showed higher leptin and IL-10 levels and lower adiponectin and TNF-alpha levels compared to children with no obesity and asthma." (PMID 36291398, 2022). "We sought to determine the influence of completion of a calorie-restricted low energy liquid diet (LELD) on leptin, adiponectin and in particular, the LAR in a cohort of patients with severe obesity (with and without T2DM)." (PMID 35662920, 2022). "Therefore, the findings from the present data suggest that obesity may be independent of ghrelin concentration but is characterized by hyperleptinemia, which is attributable to increased visceral adiposity and leptin resistance invoked by hypothalamic inflammatory mediators." (PMID 34556775, 2021). "Thus, it seems that obesity may promote carcinogenesis regardless of the presence of leptin." (PMID 34068679, 2021). "The significantly lower NEFA concentrations observed in 6- to 8-year-old girls with obesity disappeared when comparing NEFA levels between girls with and without obesity after adjusting by leptin." (PMID 35071145, 2021). "As previously indicated, IGFBP2 is reported to protect against diabetes and obesity onset and here a negative correlation between circulating IGFBP2 and insulin, glycemia, leptin and body weight was found in males." (PMID 34975768, 2021). "On the contrary, no influence of leptin levels on the differences in NEFA and insulin concentrations between children with and without obesity was observed in 12- to 16-year-old children." (PMID 35071145, 2021). "Overall, a positive correlation was observed between serum concentration of leptin and CRP independent of the obesity indices." (PMID 33680494, 2021). "Although leptin upregulates TRH expression, sex differences were not reported before and our results point to significant sex differences in TRH expression in obesity." (PMID 34154608, 2021). "In the children with obesity group, ALT and BChE levels correlated with anthropometric measurements, insulin resistance, and lipid parameters, leptin, interleukin-6, CRP, and sICAM-1 while BChE levels negatively correlated with adiponectin." (PMID 33665176, 2021). "On the other hand, leptin mutant ob/ob mice were shown to have increased peripheral Foxp3+ CD4+ Treg cells compared to WT mice, further supporting the role of leptin, and not obesity alone, in decreasing Treg cell proportions." (PMID 33584724, 2020). "Secretion of adipocyte and obesity related proteins IGF, PAI, and Leptin were increased in AMMI compared to AMMI without macrophages." (PMID 32524217, 2020). "Understanding the impact of obesity on the immune response to IAV has been accomplished using genetically obese (OB) mice, namely, ob/ob mice (strain B6.Cg-Lepob/J) lacking the leptin signaling molecule, and diet-induced models of obesity (DIO)." (PMID 32127459, 2020). "Obesogenic diet induced the development of obesity in both males and females (P < 0.001, factor ‘diet’, repeated measures ANOVA), and prenatal exposure to leptin did not significantly affect the BWs or BW gain of the female and male offspring." (PMID 31703240, 2020). "Whilst we observed a positive correlation between obesity and ANGPTL5, leptin did not correlate with increasing ANGPTL5." (PMID 31396158, 2019). "The absence of obesity in mice with RYGB early in life and exposure to high-fat diet for 50 weeks was also indicated by the normal plasma leptin levels." (PMID 31133715, 2019). "In the current study, however, both adiponectin and leptin levels increased at AE-IPF, and the mechanism of action of these adipokines does not seem to be simple like in obesity or diabetes mellitus." (PMID 31324858, 2019).
Obesity (continued). "NMU knockout mice studies showed that mice develop obesity and NMU plays an important role in the regulation of feeding behaviour and energy metabolism independent of the leptin signalling pathway." (PMID 31492042, 2019). "Consistently, mice lacking leptin (ob/ob mice) or the LEPR (db/db mice) are characterized by hyperphagia and decreased energy expenditure, resulting in severe morbid obesity." (PMID 30224299, 2018). "In conclusion, our study showed that higher leptin and lower adiponectin predicted PTS in relatively young DVT patients regardless of obesity." (PMID 29720688, 2018). "Our findings showed that lower adiponectin and higher leptin measured 3 months after DVT, regardless of obesity, can independently predict PTS, which suggests novel links between adipokines and thrombosis." (PMID 29720688, 2018). "To investigate the relationship between FEN and leptin signalling and determine effects on FGF21 levels in non-diet-induced obesity, we used the Leprdb genetic mouse model." (PMID 28256636, 2017). "Our analysis of leptin levels in subjects with IIHS and SA did not demonstrate a correlation between CSF and serum leptin as is seen in obesity and SA, i.e. “leptin resistance”." (PMID 28929972, 2017). "To test the hypothesis that altered plasma levels of insulin, leptin, and adiponectin are causative for EI of metabolic disorders in DIO models, we induced such hormonal changes in the absence of obesity and most of its complication in F0 male mice by administration of dexamethasone." (PMID 26662513, 2016). "Rather than rely solely on BMI as our obesity measure, we also measured WC, WHR, blood leptin levels, and %BF and fat mass by bioelectric impedance analysis." (PMID 27336586, 2016). "Animals with impaired leptin pathways do not develop KOA, even in the presence of extreme obesity, indicating that increased loading cannot explain cartilage degeneration alone." (PMID 26006054, 2015). "Obesity may not be only associated with lung mechanics, such as airway closure during tidal breathing and reduced expiratory residual capacity, but also with a high expression of certain inflammatory mediators, such as tumor necrosis factor (TNF)-α, interleukin (IL)-6, and leptin." (PMID 25658739, 2015). "PTP1B inhibits both insulin and leptin signaling and mice lacking PTP1B are more sensitive to both leptin and insulin and resistant to diet-induced obesity." (PMID 25147530, 2014). "To further confirm that the lack of ELOVL6 did not influence the development of obesity and diabetes, we generated mice that lacked ELOVL6 and leptin (Elovl6−/−;ob/ob mice)." (PMID 25281760, 2014). "The present results show that LEP A19G, LEP G2548A; LEPR K109R and LEPR Q223R SNPs are unlikely to be a relevant obesity marker among Malaysians, at least among the Kampar suburban population, but were associated with ethnicity." (PMID 24947733, 2014). "Baseline biomarkers in 2000-4 (CRP, IL-6, sTNFR2, leptin, lipocalin 2 and A-FABP) had significantly positive correlation with indices of obesity WC and BMI while adiponectin had significant negative correlation." (PMID 24205276, 2013). "We observed no changes in the mRNA expressions of leptin and adiponectin from adipocytes between OB-1- and saline-treated rats with HFD-induced obesity group." (PMID 23533517, 2013). "Previous studies on sex differences in the relationship of leptin to CRP showed that either the relationship was similar in men and women independent of obesity or that the independent relationship was seen only in women." (PMID 24371525, 2013). "And, regardless of sex and obesity status, leptin emerged as a stronger contributor to pubertal HOMA-IR than FAT%, waist circumference, or BMI z-score, which were traditional measurements of obesity." (PMID 23316228, 2012). "Leptin showed a strong and independent predictor of HOMA-IR, in boys (P < 0.001) and girls (P < 0.001), regardless of obesity status." (PMID 23316228, 2012).
Obesity (continued). "Similarly, indole-3-propionic acid (IPA) showed anti-obesity effects in diet-induced but not genetic obesity, explained by an IPA-mediated increase of sensitivity to leptin, with C. sporogenes boosting IPA levels and reversing weight gain." (PMID 40917104, 2025). "Visceral adipocyte geometries exhibited significant positive correlations with serum leptin levels and LEP mRNA expression in participants without obesity, as well as a trend toward a positive correlation with serum leptin levels in participants with obesity." (PMID 41271970, 2025). "Moreover, leptin treatment does not mitigate the enhanced feeding and obesity in these mice, suggesting that the body weight regulation by ARC GABA neurons and the anti-obesity effects of leptin are not solely dependent on AgRP neurons." (PMID 40130157, 2025). "The presence of leptin resistance in the MUO phenotype may explain the more dysregulated metabolic and inflammatory state in this phenotype independent of obesity." (PMID 39145170, 2024). "In our study, men had higher values for BMI and waist circumference than women, which may indicate that their obesity status was worse and the UPF test meal was not able to decrease their leptin levels." (PMID 39771019, 2024). "However, we found that while adiponectin levels were higher among those with a normal BMI and without diabetes, leptin and CRP levels were higher in individuals with overweight, obesity, with prediabetes and diabetes." (PMID 38585953, 2024). "To further explicitly distinguish the specific impact of OSAS and obesity on systemic immunological balances, we analyzed plasma levels of adiponectin, leptin, lipocalin and metalloproteinase 9 (MMP-9) from normal weight OSAS patients and patients with obesity without OSAS using ELISA measurements." (PMID 38172514, 2024). "The findings suggest that leptin may mediate the link between obesity and HF in the absence of CAD, but that obesity’s impact on HF in those with CAD is likely independent from leptin." (PMID 39682585, 2024). "Moreover, GDF15 which been positively associated with NAFLD-NASH progression, was increased in children with obesity of MASLD or MetS and leptin increased only in subjects of MASLD but not MetS." (PMID 39227971, 2024). "In mice, obesity activates the MAPK pathway, suggesting that other biomarkers might also be involved through this pathway; stimulating leptin expression independent of hCG levels." (PMID 36520252, 2023). "TSH is involved in obesity through 1) insulin inhibited deodinase (less T3, high T4), which provides no negative feedback and resulting in high TSH, and 2) leptin is a stimulator of TRH (hypothalamus) which could increase TSH." (PMID 38720938, 2023). "On the other hand, treatment with ESGA at increasing doses of 50, 100, and 200 mg/kg, failed to attenuate or reverse obesity and did not prevent increases in fat pad accumulation, glucose and insulin levels, HOMA-IR levels, or the circulatory levels of leptin in HFD-fed rats." (PMID 38004149, 2023). "Furthermore, LEP expression in obese PCOS patients was remarkably upregulated compared to that in NCs and PCOS patients without obesity." (PMID 37562217, 2023). "This cross-sectional study has the novelty of showing the relationship between the characteristics of the obesogenic environment and non-traditional biomarkers of obesity in children, such as body adiposity assessed by DXA and pro-inflammatory adipokines (leptin and RBP4)." (PMID 37559196, 2023). "When examining the correlation between the gut microbiota distribution and obesity-related markers, Firmicutes displayed a positive correlation with TC, HDL-C, LDL-C, and leptin, whereas B. vulgatus demonstrated a negative correlation with TC, LDL-C, and fasting glucose." (PMID 36839173, 2023). "Conversely, other studies observed no alterations in leptin levels in OSA patients, hypothesizing that increased levels of leptin originated from obesity rather than sleep disorders." (PMID 36760691, 2022).
Obesity (continued). "Interestingly, while brain-targeted SHP2 gene invalidation translated into severe weight gain, systemic SHP2 inhibition did not worsen the obesity phenotype of the HFD-fed mice, probably because leptin signaling was already blunted." (PMID 36140242, 2022). "In ob/ob mice, obesity and hepatic steatosis were refractory to APF treatment without leptin." (PMID 36046814, 2022). "Moreover, we examined the relationship between VFA and obesity-related clinical factors, such as the presence of non-alcoholic fatty liver disease (NAFLD) and serum leptin and adiponectin levels." (PMID 35887911, 2022). "Higher leptin concentrations may partially explain the effect of obesity on thyroid function, perhaps through the effect of leptin on TSH secretion, as this increase has been shown to be correlated with leptin regardless of BMI." (PMID 35399935, 2022). "In obesity and hyperleptinemia, negative feedback control of leptin signaling occurs due to the increased expression of SOCS3 inhibiting the phosphorylation of JAK2, thus contributing to the onset of leptin resistance." (PMID 35897769, 2022). "Compared to people with obesity without BED, those with BED have higher levels of leptin." (PMID 35758834, 2022). "Multiple toxicities in obesity and T2DM including the absence of leptin cellular signaling may result in aMGCs in the db/db models to a much greater extent as compared to the BTBR ob/ob models." (PMID 34063911, 2021). "Interestingly, the effect of obesity on absolute REE is not observed in the 8–10 year-old group, in which serum leptin concentrations correlate with the REE/FFM (r = 0.48; p = 0.011)." (PMID 33917063, 2021). "Unlike leptin, there were no significant changes of the systemic levels of adiponectin, resistin, and progranulin, which has recently been shown to correlate positively with CTRP-3 serum levels in obesity." (PMID 33562308, 2021). "In conclusion, REE/FFM is not affected by obesity or gender, while the effect of age on absolute REE is gender-dependent and leptin may influence the REE/FFM in 8–10 year-olds." (PMID 33917063, 2021). "Obesity per se may increase AHR without inflammation and the increase in mucus and inflammation by IL-33 combined with leptin enhanced AHR in obesity." (PMID 34074279, 2021). "MC4R is a downstream target of leptin signaling and mice lacking MC4R developed obesity." (PMID 33716966, 2021). "Interestingly, the effect of obesity on REE is not observed in children aged 8–10 years, which is the only age group in which serum leptin levels are positively correlated with REE/FFM." (PMID 33917063, 2021). "For example, the difference in expression levels of each of the 13 obesity-related genes between PAAD and PCPG types of cancer was not statistically significant, and the difference in the expression levels of LEP and MC4R in the 21 types of cancer was not significant." (PMID 33299884, 2020). "When the whole population was studied (participants with or without obesity), weight, BMI, FM, LBM and leptin were positively correlated with aBMD at all bone sites, while osteocalcin (OC), log sCTx, Trap-5, adiponectin and log irisin were negatively correlated." (PMID 32316563, 2020). "Obesity alone, in the absence of overt disease, is frequently accompanied by subclinical systemic inflammation marked by increased circulating levels of proinflammatory indicators such as CRP and leptin." (PMID 32326613, 2020). "Additionally, leptin inhibits NPY and activates POMC, creating a negative feedback loop that prevents obesity." (PMID 32987812, 2020). "In a follow-up 2016 study, Furukawa's group described altered leptin signaling in the hypothalamus of GD3S KO mice, which may explain why these mice do not develop obesity despite greatly reduced levels of circulating leptin." (PMID 32731387, 2020). "Notably, the expression levels of the 13 obesity-related genes in PAAD between cancer tissues and the corresponding normal tissues were not statistically significant, except for LEP." (PMID 33299884, 2020).
Obesity (continued). "Moreover, ob/ob mice, a model of genetic obesity characterized by a lack of leptin, show very low levels of UGN, recovering normal levels following a leptin treatment." (PMID 30935076, 2019). "In the present study, we found that basal plasma norepinephrine, the principal catecholamine as an index of SNS activity, was persistently elevated and highly correlated with the plasma leptin concentration, but not plasma insulin, during high fat diet (HFD)-induced obesity in mice." (PMID 31682617, 2019). "Therefore, we assessed leptin transport in the early phase of HFD-diet induced leptin resistance, when patent obesity is absent." (PMID 29748097, 2018). "Whether there is a direct relationship between aberrant leptin and adiponectin levels and CRC independent of obesity, however, is not well characterized." (PMID 30379922, 2018). "In addition, although leptin levels are not significantly correlated with metabolic parameters of obesity and T2DM, strong correlations of leptin levels with insulin levels and with indexes of insulin resistance/sensitivity and β cell function." (PMID 29785210, 2018). "We observed that elevated leptin and decreased adiponectin levels measured in one point time, 3 months since the first-ever DVT episode are independent predictors of PTS regardless of inflammatory state and obesity." (PMID 29720688, 2018). "The effect of gestational hypoxia on the neonatal leptin surge, development of hypothalamic arcuate nuclei (ARH) projections and appetite that could contribute to the programming of offspring obesity is lacking." (PMID 28957383, 2017). "Therefore, we inferred that leptin, as an acute response to stress or CVD, may not be causally linked to the risk of CVD and may just reflect a state of hypothalamic leptin resistance in obesity and one of the co-occurrences of multiple vascular risk factors with obesity." (PMID 28278178, 2017). "fcHF-fed rats had similar caloric intake, body weight, adiposity, and plasma leptin concentrations as rats on the fcHS diet, indicating that the response to MTII is not explained by obesity." (PMID 26733840, 2015). "The LEP and LEPR SNPs in this study may not be an obesity marker among Malaysians in this population, but were associated with ethnicity." (PMID 24947733, 2014). "While we did not observe any group differences in leptin, MCP-1, and TNF-α, all of which are considered to be important markers of inflammation in obesity, we did observe elevated F4/80 mRNA in WAT only in the HF-SED group compared to HF-EX and chow-fed groups." (PMID 23319832, 2012). "However, neither obesity nor T2DM changed 24-hour rhythms of plasma leptin relative to cycle mean, or expression of subcutaneous adipose leptin gene expression, compared with lean subjects." (PMID 22623983, 2012). "To date, no study has evaluated endocannabinoid levels in subcutaneous adipose tissue (SAT) of subjects with both obesity and type 2 diabetes (OBT2D), characterised by similar adiposity and whole body insulin resistance and lower plasma leptin levels as compared to non-diabetic obese subjects (OB)." (PMID 20426869, 2010). "Although we found no sex-dependent programming effectsof maternal leptin on adaptation to SFD eating, its sex-specificinfluence on liver gene expression and metabolic characteristicsmay promote formation of sex differences in the developmentof diet-induced obesity in offspring." (PMID 38952707, 2024). "Thus, the setmelanotide targeting of the central leptin–melanocortin pathway could suggestively affect the BBS central ciliary dysfunction, a mechanism that failed to entirely explain BBS obesity." (PMID 37571382, 2023). "This study aimed to investigate the adiponectin/leptin ratio in women with severe obesity with and without MetS who had undergone Roux-en-Y gastric bypass (RYGB) and to characterize the biochemical, glucose, and inflammatory parameters of blood in women with severe obesity before and after RYGB." (PMID 37571250, 2023).